IL17F (interleukin 17F)
Diseases named in the same sentence as IL17F in open-access papers (continued):
Sharing a sentence is not in itself a finding about the gene and the disease.
infection (91 papers, 2010 to 2026). The state of being infected such as from the introduction of a foreign agent such as serum, vaccine, antigenic substance or organism. "IL-2, IL-5, IL-17F, IFNγ and TNFα inductions were positively associated with the infection status in the N-peptides restimulated cells (308%, 65%, 39%, 304% and 40% increase when infected, respectively, FDR < 0.1)." (PMID 35313592, 2022). "After 5 days of infection with C. albicans, real-time PCR assay showed that expression of the genes encoding Ifng, Il17a, and Il17f was attenuated in the kidneys from Trim31−/− mice compared to Trim31+/+ mice." (PMID 34362877, 2021). "So far, autoantibodies to interferon (IFN)-γ, GM-CSF, to a group of TH-17 cytokines comprising IL-17A, IL-17F, IL-22, IL-23, and to IL-6 have been found to be causative or closely associated with susceptibility to infection." (PMID 32419033, 2020). "Overexpression of genes encoding IL-17A and IL-17F was found in the mammary tissue during infection by E. coli." (PMID 33059767, 2020). "Comparing resistant versus susceptible at 0 dpi (before the experimental infection), the expression of IL17F was three times higher in resistant kids." (PMID 32178732, 2020). "Despite both types of mice show a higher fungal burden early in infection, as compared to wild-type mice, IL-17F-deficient, more than IL-17A-deficient, mice showed signs of inflammation and PMN recruitment associated with high levels of IL-17A." (PMID 23853597, 2013). "Up to now autoantibodies to four major groups of cytokines—IFN-γ, GM-CSF, to a group of TH-17 cytokines comprising IL-17A, IL-17F, IL-22, IL-23, and to IL-6—have been found to be causative or closely associated with increased susceptibility to selective infection." (PMID 32419033, 2020). "Whereas IL-17F appears to have a marginal pathogenic role in immune mediated inflammatory diseases, it exerts a crucial function in host defense against infections, as for example, against Citrobacter rodentium, a Gram negative enteropathogenic bacterium, which is equivalent of E. coli in humans." (PMID 33244315, 2020). "Moreover, we evaluated the relevance of the IL17F rs763780 SNP during human infection caused by Mtb." (PMID 31616423, 2019). "To assess whether blocking the IL-17 cytokine family axis may affect host susceptibility to M. tuberculosis H37Rv strain infection, we investigated the effect of neutralizing IL-17A or IL-17F during acute infection, in comparison to TNFα neutralization." (PMID 27853279, 2016). "The present investigation compares the effect of anti-IL-17A or TNFα neutralizing antibodies side-by-side, including TNFα-deficient mice as susceptible controls, and in addition the role of IL-17F, in a commonly used M. tuberculosis H37Rv strain infection model." (PMID 27853279, 2016). "The association of IL-17 with infection is further confirmed when increased survival rates and decreased bacterial burdens in ducks infected with R. anatipestifer occur after expression levels of IL-17A and IL-17F cytokines are downregulated using berberine treatment." (PMID 34805416, 2021). "Both mouse strains have higher levels of TNFα, IL-6, IL-17A, and IL-17F in whole stomach homogenates after infection, illustrating that the type 3 model of gastric mucosal inflammation and C. albicans pathogenesis is applicable in both C57BL/6 and BALB/c mice." (PMID 39347572, 2024). "The IL-17A, IL-17F, and IL-22-producing type 3 ILCs were significantly higher in the ace2Δ after 14 days post-infection." (PMID 39475280, 2024). "Expression of both IL-17A and IL-17F was downregulated at 4 hours post-infection in both RNA-seq and qRT-PCR analyses, displaying minimal variation." (PMID 37930983, 2023).
infection (continued). "IL-17A and IL-17F evolved to protect against infection via the regulation of protective responses against infections at mucosal and epithelial surfaces, including the intestines, skin, lungs, and oral cavity." (PMID 37373452, 2023). "At 24 hours post-infection, IL-17A expression was upregulated across both methods, while IL-17F expression was upregulated in RNA-seq and downregulated in qRT-PCR, displaying minimal variation." (PMID 37930983, 2023). "In the present study, quantitative real-time RT-PCR analysis revealed that after infection with Mtb, the expression of Il17f was increased in H1-DDA/TDB-vaccinated IL-17A−/− mice in comparison to vaccinated C57BL/6 mice." (PMID 34351501, 2021). "In the present study, IL17F was the gene showing the most significant expression difference at day 0 of infection, having an expression three times higher in resistant compared with susceptible kids." (PMID 32178732, 2020). "Among the Th17-related signaling pathways, ‘Th17 Activation Pathway’ and ‘Differential Regulation of Cytokine Production in Macrophages and T Helper Cells by IL17A and IL17F’ were commonly activated in canine PBMCs at all times of infection." (PMID 33520738, 2020). "IL-17A and IL-17F reduced the number of intracellular bacteria in an ex vivo model of infection using pediatric intestinal biopsies suggesting their importance in intestinal immunity." (PMID 31427597, 2019). "The recruitment of neutrophils to the site of infection as well as the induction of Il17f and S100a9, two of the most strongly induced genes by SC5314 on day 1 post-infection, was comparable in both conditions." (PMID 30873177, 2019). "Regarding the role of IL17A and IL17F in the immunity against infections, these cytokines seem to have redundant functions in the defense against Staphylococcus aureus, although both cytokines are necessary in the control of Citrobacter rodentium infection." (PMID 31616423, 2019). "Following infection with Campylobacter, the immune response in the cecal tissues appears to be more focused on the Th17 pathway featuring IL-6 induction with IL-17A and IL-17F responses, as compared to that observed in the ileum tissues." (PMID 29753324, 2018). "We set out to characterize cells with the potential to produce IL-17A and IL-17F in response to C. albicans at the site of infection." (PMID 29782555, 2018). "Because Il17a and Il17f transcript levels are maximal on day 1 post-infection with C. albicans strain SC5314, we focused our analysis on this time point." (PMID 29782555, 2018). "At d1 post-infection, IL-17a and IL-17f were upregulated 25,000 and 15,000-fold, respectively, compared to controls, and ≈20,000 and ≈1,500-fold compared to sterile bead-instilled animals." (PMID 28680858, 2017). "Overall, expression of IL-17A and IL-17F genes during infection raise the point of the contribution of these cytokines to the defence of the udder against bacterial infection." (PMID 26062913, 2015). "Similar to infection, we observed a robust expression of the Th17-related genes RORγt, IL-23p19, IL-17F, IL-21 and IL-22." (PMID 26490738, 2015). "From the data presented in this report, we can clearly conclude that expression of IL-17A and IL-17F genes is induced approx. 100-fold upon infection by E. coli." (PMID 26062913, 2015). "By contrast, cytokines involved in Th17 signal transduction, such as IL-17A, IL-17F or IL-21, were highly up-regulated after infection, and the Th17 pathway is known to contribute to inflammation and influx of neutrophils to the site of infection." (PMID 25719526, 2015). "In the lesion, IL-17F mRNA expression was present all over the infection course, from day 2 to day 360 p.i., with a peak of 5.63-fold at day 8 compared to control mice." (PMID 24637903, 2014). "To directly prove the role of IL-22, we evaluated levels of IL-22, as well as of companion cytokines, such as IL-17A and IL-17F, in infection and the consequences of IL-22 inhibition or administration." (PMID 23853597, 2013).
infection (continued). "This is the first study, to our knowledge, to demonstrate expression of both IL-17A and IL-17F in the same CD4+ T cell in a human infection." (PMID 23451159, 2013). "In contrast, the concentrations of IL-17F, and its soluble receptor IL-17RA were the highest in infection-free controls." (PMID 22969818, 2012). "Beyond the known inflammatory mediators, we identified IL-22, IL-17A and IL-17F as highly upregulated cytokines and as first responders to infection during the innate phase of the host immune response." (PMID 22675469, 2012). "Plasma concentrations of pro-inflammatory IL-17 family members IL-17A, IL-17B, IL-17F and their common soluble receptor subunits, sIL-17RA and sIL-17RB, were quantified in AE patients with different states of disease and in infection-free controls." (PMID 22969818, 2012). "Recently, several studies have investigated the important role of TNF superfamily (such as TNFSF-15) and IL-17 family (such as IL-17F) in the regulation of immune response during infection of Eimeria." (PMID 22754694, 2012). "After 8 hours of infection, at the more acute phase, the virulent strain had induced an extensive increase in many cytokines, particularly IL-22, IL-17A and IL-17F (132 to 233 fold)." (PMID 22675469, 2012). "those that are highly upregulated by infection of both the virulent and avirulent strains (IL-22, IL-17A, IL-17F and iNOS); and iv." (PMID 22675469, 2012). "Production of IL-17A and IL-17F by cells from the spleen and lymph nodes of infected mice peaked by days 10–20 post-infection and gradually decreased by day 32 post-infection." (PMID 22577359, 2012). "In response to infection with Candida albicans, IL-17A, IL-17F and IL-17RA were up-regulated in mucosal tissues." (PMID 22174673, 2011). "We detected a significant upregulation of both Il17a and Il17f in young VI mice (VI vs. V), while only Il17a was found upregulated in young NI mice (NI vs. N), which suggested a more robust Th17 response following vaccination and subsequent infection." (PMID 38932347, 2024). "Infection with some HPV types (i.e., high-risk HPV-35, -39, and -68) was associated with higher cervicovaginal cytokine concentrations, particularly of IL-17A, IL-17F, TNF-α, IL-25 and IFN-γ." (PMID 36992467, 2023). "It was recently demonstrated that IL-17A and IL-17F are drivers of adipocyte lipid usage in adipocytes during infection and, moreover, promote infection-induced cachexia, suggesting that it may drive lipid usage in other cell types, including hepatocytes." (PMID 37371074, 2023). "In contrast, the level of IL-17F, an inflammatory cytokine, was significantly increased at 7 dpi (151.1 ± 19.3 pg/mL, p = 0.0003) and 21 dpi (89.7 ± 20.6, p = 0.0187) compared to the pre-infection (33.7 ± 11.2 pg/mL) time point." (PMID 36851142, 2023). "Indeed, transcriptome analyses revealed increased expression of proinflammatory IL17A, IL17F, and RORC (which encodes the IL-17 transcription factor RORγt38) genes in rAAV-IL-27p28-treated mice early during infection." (PMID 36028492, 2022). "From the transcriptomic analysis of bovine immune cells (PBMCs), it was suggested that infection through the epithelial cells elicited prolonged Th17-derived immune response, as indicated by upregulation of IL-17A, IL-17F and RORC until 120 h p.i., compared to directly infected PBMCs." (PMID 33273606, 2020). "However, IL-17A and IL-17F expression levels were higher at all time points post-infection in duck spleens." (PMID 31519917, 2019). "Additionally, IL17F, an important pro-inflammatory cytokine, was expressed significantly higher at 9 hpi in infected cells and expression level increased throughout the infection." (PMID 31725732, 2019). "These seemingly contradictory results have arisen not least because of indirect assessments of IL-17A production during infection by either measuring Il17a and Il17f transcripts in crude tongue extracts or monitoring IL-17A promoter activity in Il17aeYFP fate reporter mice." (PMID 29782555, 2018).
infection (continued). "The Th17 and γδ T cells are major sources of IL17A and IL17F in response to infection." (PMID 28447937, 2017). "Compared to IL17A, IL17F was found to be a more potent inducer of CXCL5, a known neutrophil recruiter, indicating that F. hepatica may avoid excessive neutrophil recruitment during infection by suppressing the IL17F/CXCL5 axis." (PMID 27661612, 2016). "Indeed, IL-17A and IL-17F expression in the infected tissue is induced rapidly after infection, suggesting that the relevant source of IL-17 for fungal control is produced by innate and not by adaptive cells." (PMID 26274976, 2015). "Susceptibility to such a narrow spectrum of infections is surprising and indicates that the IL-17 pathway and, in particular, IL-17A and IL-17F play a particular and non-redundant role in host defense against mucocutaneous infections with C. albicans." (PMID 26274976, 2015). "We found elevated levels of IL-22 through the infection in IDO1-deficient mice in which high levels of IL-17F, but not IL-17A, were also higher as compared to wild-type mice." (PMID 23853597, 2013). "Expression levels of interleukin (IL)-4, IL-10, IL-13 and tumor necrosis factor (TNF)-α were significantly up-regulated while interferon (IFN)-α, IFN-β, IFN-γ, IL-1β,IL-2, IL-3, IL-15, IL-17F, IL-18 and colony-stimulating factor (CSF)-1 were markedly decreased in PBMCs at all stages of infection." (PMID 24358317, 2013). "Infection with avirulent S. flexneri led to a substantial upregulation of only IL-22 (3.3 fold), although upregulation (1.4 fold) could also be detected for IL-17F and TNF-α." (PMID 22675469, 2012). "Indeed, we determined that during T. cruzi infection not only IL-17A but also IL-17E and IL-17F are produced during the peak of the infection." (PMID 22577359, 2012). "We analyzed levels of pro-inflammatory IL-17 members (IL-17A, IL-17B and IL-17F) as well as their soluble common receptors (IL-17RA and IL-17RB) in clinically staged AE patients, that is, cured, stable, and progressive AE, and in infection-free controls." (PMID 22969818, 2012). "After infected with Yersinia pseudotuberculosis, the highest infection-induced immunomodulatory genes were those of the major proinflammatory cytokines: interleukin-1 alpha (il1a), interleukin-1 beta (il1b), interleukin-6 (il6), interleukin-17F (il17f) and interferon gamma (ifng)." (PMID 36059501, 2022). "Moreover, pathways such as “IL-10 signaling,” “IL-6 signaling,” “NF-kB signaling,” “Acute phase response signaling,” and “Differential regulation of cytokine production in macrophages and T helper cells by IL-17A and IL-17F” showed strong regulation of immunity-related genes during early infection." (PMID 31969876, 2019). "Besides, it has been also reported that MAIT cells from TB produced higher levels of IL17F at the site of infection than in the periphery.Thus, our present findings, together with previous reports, suggest a protective role for IL17F during the immune response of the host against mycobacteria." (PMID 31616423, 2019). "One of our hypotheses associated to a direct role of IL17F in TB, implies that different amounts of this cytokine could influence the levels of IL17A and IFNG secreted by HD and TB, affecting the onset of the infection." (PMID 31616423, 2019). "Hence, IL-17A and IL-17F play distinct roles in extracellular versus intracellular infections." (PMID 27853279, 2016). "Infection increased the populations of ILC2, Il17f+ILC3, Cd8+ T cells, and regulatory T cells (Tregs)." (PMID 40127923, 2025). "We examined IFNγ-, IL17A-, and IL17F-producing T cell subsets, including γδ+, CD4+, and CD8+ T cells, after 14-days post-infection." (PMID 39475280, 2024). "A strong interaction between dietary APS and NE infection was observed in relation to IFN-γ, IL-17F and IL-22 (P < 0.05) in ileum." (PMID 35265068, 2022).
infection (continued). "The Th17 response-related pathways (IL-6 Signaling, IL-23 Signaling Pathway, Role of IL-17F in Allergic Inflammatory Airway Diseases, Th17 Activation Pathway, LXR/RXR Activation, and PPAR Signaling) were commonly expressed at all infection times." (PMID 33520738, 2020). "Although the concentrations of IFNα, IL-17F, and VEGF remained elevated in the convalescent phase of the infection, levels of all other chemokines/cytokines decreased again and were comparable with the concentrations of the control group." (PMID 31769398, 2020). "Unlike previous studies with Helicobacter pylori where infection causes adenocarcinoma and produces high levels of IL-17 and IL-21, only moderate increase in signature cytokines secreted by Th17 cells, such as IL-17, IL-17F, IL-21, and IL-22, was observed in our experiments." (PMID 29445365, 2018). "Th17 cells produce well-known soluble molecules such as IL17A, IL17F and IL21 which are important for neutrophil recruitment, infection clearance and delivery of antimicrobial peptides." (PMID 25495206, 2014). "In this study, expression levels of IL-4, IL-10, IL-13 and TNF-α were significantly up-regulated while the expression levels of IL-1β,IL-18,IFN-γ, IL-2, IL-15, IL-17F, IFN-α, IFN-β, IL-3 and CSF-1 were markedly decreased in PBMCs at all stages of infection." (PMID 24358317, 2013). "Early after infection of C57BL/6 mice with Mtb real time RT-PCR of lung homogenates was conducted to compare gene expression of Il22 with the expression of Il17a, Il17f, Il12b, and Il23p19." (PMID 23460846, 2013). "Th17 cells exert their biological effects via the secretion of IL-17A, IL-17F, IL-6, IL-22 and TNF-α, which signals neutrophils to move towards the site of inflammation and play an infection-fighting role in the early stage of the immune response." (PMID 23403648, 2013). "Second, the importance of IL-17F during craniotomy infection remains an open question since the cytokine was absent in Il17a/f–/– mice, whereas only IL-17A was neutralized in Ifng–/– animals." (PMID 39989461, 2025). "Subsequent examination of IL-17A-related genes revealed a lack of significant expression, except for IL-17F, which was downregulated at the 4-hour time point post-infection." (PMID 37930983, 2023). "Our results revealed that IL-10, IL-8, IL-6, IFN-, IL-17A, and IL-17F levels in patients with bacterial lung illness were abnormally higher than those without infection." (PMID 36319826, 2022). "However, we observed that Th17-related genes (IL-17F, IL-17RD, IL-23, and IL23R) were significantly downregulated, which is similar to previous findings on F. hepatica-induced infection in ovine peripheral blood mononuclear cells." (PMID 35320269, 2022). "Furthermore, uncontrolled infections with BCG or Mtb were reported in individuals with defects in IL17A and IL17F production." (PMID 31616423, 2019). "IL17F expression was higher than IL17A in this study (signal intensity of IL17A and IL17F: 51 and 218, respectively) and significantly up-regulated in infected macrophages after 9 hours of infection." (PMID 31725732, 2019). "Our previous study described that co-infected Ss infection with active or latent TB has significantly reduced Type 1 (IFN-γ, TNF-α, and IL-2), Type 17 (IL-17A and IL-17F) and increased regulatory as well as Type 2 (IL-4, IL-5, and IL-13) cytokines when compared to TB infection alone." (PMID 30897083, 2019). "Moreover there is a group of molecules, including LTA, LTB, IL21, IFNAR2, CXCR3, IL17F and CD40LG, whose expression increased over the course of USA300 infection." (PMID 25719526, 2015). "Il22−/− mice, with or without FT, displayed induction of IL-17A, IL-17F, and IL-10 upon infection." (PMID 41361166, 2025). "IL-17A, IL-17F, IL-17C, and IL-17E perform a variety of yet not fully known roles mediating inflammation in autoimmune, allergy, and chronic inflammatory disorders in addition to functioning in host defence against infections at epithelial interfaces." (PMID 37373452, 2023).